APOE (apolipoprotein E)
Diseases named in the same sentence as APOE in open-access papers (continued):
Sharing a sentence is not in itself a finding about the gene and the disease.
Alzheimer disease (continued). "Finally, Alzheimer disease is a complex genetic disease and any modulation of network breakdown due to APOE ε4 here observed likely occurs in the context of attenuation by a host of other genetic and environmental factors." (PMID 28578156, 2017). "The ε4 allele of apolipoprotein E (APOE4) is the strongest genetic risk factor for Alzheimer’s disease (AD), but not all APOE4 carriers will develop the disease suggesting that APOE genotype interacts with other factors to modulate Alzheimer’s risk." (PMID 28612048, 2017). "A genetic variant near the APOE gene, however, was associated with these risk factors and strongly associated with Alzheimer’s disease (P<5×10−464), and none of the associations remained after we excluded the pleiotropic variant." (PMID 29212772, 2017). "Although the association between apolipoprotein E (APOE) genotype and disease progression is well characterized in patients with Alzheimer’s disease, such a relationship is unknown in patients with subcortical vascular cognitive impairment." (PMID 28507298, 2017). "Indeed the two nsSNPs in APOE make up a set of haplotypes, of which one is known as ε4 and is well documented to be implicated in the pathogenesis of both AMD and Alzheimer’s disease (AD)." (PMID 28774272, 2017). "It was shown that higher serum IGF-1 levels in middle age were associated with risk of Alzheimer’s disease in older age, independent of Apolipoprotein E (ApoE) genotype." (PMID 27544533, 2016). "Predictive tests for Alzheimer’s disease can take many forms, including apolipoprotein E genotype testing, positron emission tomography imaging for cerebral amyloid pathology, cerebrospinal fluid tests, or tests for other biomarkers individually or in combination." (PMID 27955707, 2016). "The increase in APOE levels induced by probucol was shown to improve Alzheimer’s Disease Assessment Scale-Cognitive subscale (ADAS-Cog) scores and to inversely correlate with phosphorylated tau in the cerebrospinal fluid (CSF), a marker of neuronal damage in AD subjects." (PMID 27457486, 2016). "Many studies have demonstrated a correlation between APOE genotypes and coronary heart disease and Alzheimer’s Disease (AD), especially with the APOE ε4 genotype; however, the relationship between APOE genotypes and diabetes or blood glucose levels has not been confirmed." (PMID 26998902, 2016). "Comment: This patient's presentation was typical for type 3 Alzheimer's disease in age of onset, preceding depression, ApoE non- ε4 genotype, executive dysfunction, predominantly non-amnestic onset, negative family history, and strong response to stress and sleep." (PMID 26870879, 2016). "We applied the Brain Age Gap Estimation (BrainAGE) method to examine the impact of the Apolipoprotein E (APOE) genotype on structural brain aging, utilizing longitudinal magnetic resonance image (MRI) data of 405 subjects from the Alzheimer’s Disease Neuroimaging Initiative (ADNI) database." (PMID 27410431, 2016). "They calculated an additive genetic risk score and compared Alzheimer's disease status prediction performance of age, gender, and the apolipoprotein E (APOE)ε4 allele using logistic regression with and without the additive genetic risk score." (PMID 26075270, 2015). "In hypothesis-driven tests, there was significant association between general cognitive function and four genes previously associated with Alzheimer's disease: TOMM40, APOE, ABCG1 and MEF2C." (PMID 25644384, 2015). "In particular, oral administration of bexarotene in a murine model of Alzheimer’s disease has been shown to enhance clearance of soluble amyloid β (Aβ) peptide in an apolipoprotein E (apoE)-dependent manner while improving cognitive, social, and olfactory deficits." (PMID 25844636, 2015). "Such individuals might be under-represented in the APOE+ and/or amyloid+ groups, which are enriched for Alzheimer’s disease, and thus more prevalent in the APOE− and amyloid− groups." (PMID 25012224, 2014).
Alzheimer disease (continued). "The patient carrying this variant (PSEN1 p.I168T) was diagnosed at 86 years of age, heterozygous for APOE ε4 allele (ε2ε4), presented an advanced Alzheimer's disease (Braak V), and did not report any positive family history." (PMID 25104557, 2014). "This process may be regulated by the SNCA and APOE genes, which are involved in cholesterol metabolism and the pathogenesis of Alzheimer's disease." (PMID 24587296, 2014). "These include people who are homozygous for a common variant in APOE, ApoE4, whom are 10 times more likely to develop Alzheimer’s Disease relative to persons not harboring the ApoE4 variant." (PMID 24904423, 2014). "Apolipoprotein E also plays a vital role in the pathogenesis of Alzheimer’s disease, where apolipoprotein E is found in the amyloid plaques and neurofibrillary tangles characteristic of Alzheimer’s disease." (PMID 24410762, 2014). "Apolipoprotein E (apoE) is a 299-amino acid protein, initially discovered as an exchangeable apolipoprotein that modulates lipoprotein metabolism and also plays an important role in neurodegenerative diseases such as Alzheimer's disease." (PMID 23554788, 2013). "The estimated transition probability matrix of binary cognitive status measured by COGSTAT in Alzheimer's disease patients at the age of 55 or 85, having 12 or 20 years of eduction, and carrying no, one, or two APOE- 4 alleles." (PMID 24073268, 2013). "The estimated transition probability matrix of clinical dementia rating (CDRGLOB) in Alzheimer's disease patients at the age of 55 or 85 and carrying no, one, or two APOE- 4 alleles." (PMID 24073268, 2013). "The estimated transition probability matrix of binary cognitive status measured by MMSE in Alzheimer's disease patients at the age of 55 or 85 and carrying no, one, or two APOE- 4 alleles." (PMID 24073268, 2013). "What about a patient with Alzheimer's disease who is positive for the ApoE gene?" (PMID 24058348, 2013). "ApoE, for example, is well known as an important mediator of Alzheimer’s disease." (PMID 23531341, 2013). "The estimated transition probability matrix of functional activities (FAQ) in Alzheimer's disease patients at the age of 55 or 85 and carrying no, one, or two APOE- 4 alleles." (PMID 24073268, 2013). "In addition, apolipoprotein E (ApoE) is currently considered to be an important genetic marker for late onset Alzheimer’s disease." (PMID 24063518, 2013). "The moderate consumption of alcohol has been observed to be a protective factor in non-ApoE ε4 carriers, whereas heavy drinking may accelerate the onset of Alzheimer’s disease." (PMID 24063518, 2013). "We tested for association with loci previously associated with Alzheimer’s disease risk and, despite the small size of the study, we detected associations with age at onset of Alzheimer’s disease in Down syndrome with PICALM (β = 3.31, p = 0.011) and the APOE loci (β = 3.58, p = 0.014)." (PMID 23601808, 2013). "The APOE gene plays an important role in the development of Alzheimer’s disease (AD)." (PMID 24312416, 2013). "The similarity to APOE extends to an elevated abundance in brain regions (including the hippocampus and entorhinal cortex) that are affected by the pathology of Alzheimer's disease and cerebrospinal fluid (CSF), as well as being present in amyloid plaques and binding to beta-amyloid." (PMID 24278680, 2012). "Even screening for the ApoE-4 allele, the strongest risk factor for Alzheimer ́s disease in most populations, is not generally recommended because of prognostic uncertainty." (PMID 22864986, 2012). "In addition, using immunoprecipitation with ApoE- and with mortalin-antibodies, we have found that mortalin binds ApoE in hApoE-TR mice, as well as in human brains of Alzheimer’s disease patients." (PMID 24970131, 2012). "Similar to apoE, the expression of clusterin in the brain changes significantly during development and during different kinds of neuronal injuries and increases in Alzheimer's disease." (PMID 23119149, 2012).
Alzheimer disease (continued). "Following this line of reasoning, differential APOE expression patterns - as indicated in this report - might be independent of the amyloid beta aggregation pathway in the course of Alzheimer's disease." (PMID 21283692, 2011). "The remaining 37 control subjects, 32 MCIs and 117 patients with Alzheimer's disease were different in sex distribution, apolipoprotein E (ApoE) ε4 carriers, age, and general intelligence, thus, in further analyses, data were controlled for age, ApoE ε4, and gender." (PMID 22216027, 2011). "For example, homozygotes for the APOE ε4 gene variant suffer from an increased risk of Alzheimer's disease, but many people who test positive for this allele will not develop Alzheimer's disease." (PMID 22958637, 2011). "NINJ2 SNP analysis by APOE e4 status for Alzheimer's disease patients and controls." (PMID 21674003, 2011). "Odds ratios for the association between Alzheimer's disease and APOE ε4 carriers (vs. APOE ε4 non-carriers) among different strata defined by PRNP codon 129 genotypes." (PMID 21799773, 2011). "The isoform E4 of apolipoprotein E has been shown to be closely related to Alzheimer's disease." (PMID 20140182, 2010). "Moreover, interaction between APOE and other genes should be taken into account in studying the pathogenesis of MS, as in other apoE related diseases such as Alzheimer's disease." (PMID 20613949, 2010). "Earlier onset of Alzheimer's disease: risk polymorphisms within PRNP, PRND, CYP46, and APOE genes." (PMID 21034472, 2010). "As an example, for Alzheimer's disease the APOE locus exerts a large effect compared to other loci, hence the normal assumption is more dubious and analytic calculations of predictive metrics may not be very accurate." (PMID 21151957, 2010). "Effect of APOE genotype on amyloid plaque load and gray matter volume in Alzheimer disease." (PMID 21034472, 2010). "The aim of this study is to examine the influence of the catechol-O-methyltranferase (COMT) gene (polymorphism Val158 Met) as a risk factor for Alzheimer's disease (AD) and mild cognitive impairment of amnesic type (MCI), and its synergistic effect with the apolipoprotein E gene (APOE)." (PMID 19793392, 2009). "ApoE single nucleotide polymorphisms (SNPs) Cys112Arg (Epsilon-4), and Arg158Cys (Epsilon-2) have been implicated in cardiovascular and Alzheimer's disease, but their role in colorectal cancer (CRC) has not been extensively studied." (PMID 19455140, 2009). "The apolipoprotein-E (APOE) gene has been studied extensively in regard to its relationship to aging-associated medical illness, including cardiovascular disease, geriatric cognitive decline, and late-onset Alzheimer's disease." (PMID 19890394, 2009). "Genetic and biochemical studies support the apolipoprotein E (APOE) ε4 allele as a major risk factor for late-onset Alzheimer's disease (AD), though ~50% of AD patients do not carry the allele." (PMID 18439297, 2008). "APOE genotyping is not generally offered, even though specific alleles are statistically associated with Alzheimer disease and macular degeneration, for several reasons, primarily that there is currently no specific successful intervention for these disorders." (PMID 16756678, 2006). "Since apoE is important in the pathogenesis of Alzheimer's disease (AD), we tested whether apoE treatment of neurons affected molecules important to phosphorylation of tau, such as GSK 3β, P35, and CDK5, and the phosphorylation of tau itself." (PMID 17166269, 2006). "Therefore, it is important to search for relevant interactions(s) between apolipoprotein E ε4 and Aβ in order to clarify the biological role for apolipoprotein E ε4 in Alzheimer disease." (PMID 15312232, 2004). "We also tested whether Alzheimer's disease polygenic risk score without APOE was associated with limbic-predominant age-related TDP-43 encephalopathy neuropathologic change." (PMID 42266427, 2026).
Alzheimer disease (continued). "ApoE expression, and ApoE2 in particular, may be expected to promote compensatory mechanisms, through neuronal plasticity and axonal sprouting, to mitigate symptoms in Alzheimer’s disease and related disorders." (PMID 41278832, 2025). "Additionally, we lacked data on Alzheimer’s disease biomarkers and the main genetic risk factor, APOE." (PMID 40283437, 2025). "Furthermore, epidemiological studies suggest that interactions between ApoE 4 and herpes simplex virus type-1 (HSV1) could associate with higher risk of Alzheimer’s disease." (PMID 40295730, 2025). "Nonetheless, the exclusion of individuals without APOE-ε4 alleles may omit a significant proportion of preclinical Alzheimer's disease (AD) cases." (PMID 40000321, 2025). "Testing for gene mutations causing Alzheimer's disease, such as APOE, APP, PSEN1, and PSEN2, could not be performed because the patient did not consent." (PMID 39974219, 2025). "Indeed, organoids carrying the APOE ε4 allele exhibited exacerbated neuronal dysfunction and inflammation upon HSV-1 infection, mirroring clinical data that HSV-1 positive APOE ε4 carriers are at heightened risk of Alzheimer’s dementia." (PMID 41441202, 2025). "While disorders like schizophrenia are characterised by a wide spectrum of genetic variation including a high burden of rare variants, others may be characterised by common variants of stronger effect in genes such as LRRK2 in Parkinson’s disease (PD), or APOE in Alzheimer’s disease (AD)." (PMID 41176580, 2025). "Dzianok and Kublik found that Alzheimer’s disease risk alleles of the PICALM gene may accelerate cognitive functions, such as memory and attention, in cognitively normal, middle-aged individuals carrying the APOE ε4 allele." (PMID 40710281, 2025). "At Alzheimer’s disease (AD) risk loci, qQTL analysis revealed complex regulatory architecture including variance effects at PITRM1, lower-quantile-specific effects at TMEM106B partially explained by APOE ε4 interactions, and coordinated epigenetic regulation at loci harboring CHRNE/SCIMP/RABEP1." (PMID 41377971, 2025). "This lack of response in APOE ε4 noncarriers may be due to their lower genetic susceptibility to Alzheimer's disease pathology." (PMID 40405696, 2025). "The significant differences in APOE ε4 allele frequency and Aβ positivity between SMC and CI groups in both ADNI-2 and ADNI-3 cohorts confirm APOE ε4 as a major genetic risk factor for Alzheimer’s disease (AD) and highlight the association between Aβ pathology and cognitive decline." (PMID 40766179, 2025). "ApoE4 appears to have a less effective anti-inflammatory function, even being a pro-inflammatory factor, when compared to other apoE isoforms, aggravating the neurological damage and clinical outcomes in various conditions, such as Alzheimer's disease and stroke." (PMID 39109239, 2024). "APOE ε4 might be another example of antagonistic pleiotropy as ε4 carriage appears to be both beneficial (e.g., fertility and resistance to infections) and detrimental (e.g., Alzheimer’s disease) to human health." (PMID 38509472, 2024). "Even with increasing understanding of the pleiotropic role of APOE in the pathogenesis of Alzheimer’s disease it remains difficult to define a precise therapeutic hypothesis based on the deep mechanistic understanding of the role of the different APOE isoforms in the disease." (PMID 39528861, 2024). "To demonstrate whether directly reprogrammed brain organoids can efficiently recapitulate neurodegenerative diseases such as Alzheimer’s disease, we initially generated 3D induced brain organoids derived from APOE ε4-expressing AD patient fibroblasts with a familial origin." (PMID 39185458, 2024). "Additionally, previous studies identified non-modifiable risk factors, APOE e4/e4 genotype, and family history of Alzheimer’s disease, which are also strongly associated with dementia outcomes." (PMID 38807092, 2024).
Alzheimer disease (continued). "In contrast, neither APOE nor AD-PRS scores showed robust associations with atrophy in a composite measure of regions sensitive advanced non-Alzheimer's disease-related brain aging (SPARE-BA), supporting prior evidence that this measure largely reflects age but not disease-related atrophy." (PMID 39229494, 2024). "Our finding of an interaction between APOE-ɛ4 and AD-PRS scores in relation to WMH trajectories further suggests that associations between APOE-ɛ4 and WMH load may be more evident among those with additional Alzheimer's disease risk genes, beyond APOE." (PMID 39229494, 2024). "For example, sortilin is genetically associated with Alzheimer’s disease (AD), regulates several aspects of amyloid precursor protein (APP) and amyloid-β (Aβ) trafficking and processing, and facilitates endocytic uptake of apolipoprotein E, the most important genetic risk factor for late-onset AD." (PMID 37949230, 2023). "Therefore, targeting APOE-mediated inflammatory responses as part of therapeutic approaches for Alzheimer’s disease or neurodegeneration could prove useful and should be explored further as a potential solution." (PMID 37445986, 2023). "For example, for the Late-onset Alzheimer’s Disease risk report based on the APOE gene, 23andMe® states that risk estimates may not be equally accurate across all ethnic backgrounds." (PMID 37108959, 2023). "The associations were stronger for non-carriers of the Alzheimer’s disease risk gene APOE ε4." (PMID 37091584, 2023). "The last strength of this study is that it took into account some covariables that could influence CI, such as age, BMI, employment status, educational level, drug consumption, physical activity, family history of Alzheimer’s disease, APOE genotype and the presence of depressive symptomatology." (PMID 37960158, 2023). "Interestingly, human apoE, particularly APOE4, was identified as a major genetic risk factor for Alzheimer’s disease by differential effects on amyloid-β accumulation in the brain and its vasculature, as well as for poor neurological outcome after traumatic brain injury and hemorrhage." (PMID 37111572, 2023). "Moreover, it is not reported whether and how glycogen synthase kinase‐3β (GSK‐3β), a crucial kinase in insulin resistance and Alzheimer disease‐like pathologies, play a role in linking ApoE ε4 and cognitive impairment." (PMID 37700547, 2023). "Metabolic changes may have a larger interaction with Alzheimer’s disease (AD) pathology and its consequences in individuals who do not carry an APOE ε4 allele." (PMID 37163733, 2023). "Whether the shift of ApoE secretion from an astrocytic source to a microglial origin contributes to different biological functions remains to be determined to elucidate the impact of microglial-derived ApoE in the pathogenesis of Alzheimer’s disease." (PMID 36710921, 2023). "For example, we found that the APOE gene shows hc-RAE heterozygous APOE4 allele carriers are known to have increased risks for late-onset Alzheimer’s disease, but we do not yet know how RAE may influence these risks." (PMID 36640362, 2023). "A study found that patients without the APOE-4 allele, a risk gene for sporadic Alzheimer’s disease, performed better on the Alzheimer’s Disease Assessment Scale-Cognitive Subscale (ADAS-cog) than patients with the allele after receiving treatment with medium-chain triglycerides (MCT)." (PMID 36771231, 2023). "Genetic risk factors such as APOE ε4 and MAPT (rs242557) A allele are associated with amyloid and tau pathways and grey matter changes at both early and established stages of Alzheimer’s disease, but their effects on cortical morphology in young healthy adults remain unclear." (PMID 37693814, 2023).